FLG (filaggrin)
Diseases named in the same sentence as FLG in open-access papers (continued):
Sharing a sentence is not in itself a finding about the gene and the disease.
atopic dermatitis (continued). "Loss-of-function mutations within the filaggrin gene strongly predispose patients to atopic dermatitis, while the expression of filaggrin is reduced in patients with atopic dermatitis without filaggrin gene mutations." (PMID 37298299, 2023). "The discovery in 2006 that loss-of-function mutations in the filaggrin gene (FLG) cause ichthyosis vulgaris and can predispose to atopic dermatitis (AD) galvanized the dermatology research community and shed new light on a skin protein that was first identified in 1981." (PMID 35628125, 2022). "Furthermore, the expression levels of HRNR and FLG-2 were shown to be significantly reduced in the skin of patients with atopic eczema, as was also demonstrated for FLG." (PMID 36013110, 2022). "The EDC was originally identified in the human and mouse genomes and mutations in specific EDC genes, such as filaggrin (FLG) and late cornified envelope (LCE) 3B/3C were found to be associated with prevalent skin diseases, atopic dermatitis and psoriasis, respectively." (PMID 35948609, 2022). "Among the 41 Single Nucleotide Polymorphisms (SNPs) screened for mutation sites in more than 3 patients, filaggrin gene FLG rs192116923 T>G and FLG rs75235053 C>G were newly found to be associated with EA patients with atopic dermatitis (AD) (P <0.001) and severe EA (P=0.032), respectively." (PMID 34484176, 2021). "When challenged with an allergen, atopic dogs attempt to compensate for the insult with an increased production of filaggrin, and an increased expression of enzymes responsible for filaggrin degradation has been described in experimental models of canine atopic dermatitis." (PMID 34357916, 2021). "While in people, filaggrin loss-of-function mutations have been identified as major risk factors for the development of atopic dermatitis, this does not appear to be case in most breeds of dogs." (PMID 34357916, 2021). "This hypothesis is supported by the fact that we have detected variants in filaggrin (FLG) in patients from this cohort, some of which are known to be associated with ichthyosis vulgaris and atopic dermatitis." (PMID 34390440, 2021). "In skin diseases such as atopic dermatitis, low filaggrin values are observed in affected areas." (PMID 33187177, 2020). "Despite the critical role of filaggrin mutation in barrier dysfunction of patients with atopic dermatitis, the association of miRNAs with barrier abnormalities in this disease, independent of filaggrin, has been also suggested." (PMID 32806619, 2020). "Thus, characterizing the genetic abnormalities in filaggrin is important for understanding the outside-inside mechanism in atopic dermatitis." (PMID 32326002, 2020). "Human filaggrin (FLG) plays a key role in epidermal barrier function, and loss-of-function mutations of its gene are primarily responsible for the development of human atopic dermatitis (AD)." (PMID 32308144, 2020). "It occurs not as a driver but as a consequence of eczema, and filaggrin deficiency has been implicated in the pathogenesis of atopic dermatitis due to its significant role in homeostasis of the skin." (PMID 31781276, 2019). "Notably, both FLG and OVOL1 were included among 31 genes identified as being significantly linked to susceptibility to atopic dermatitis by genome-wide association studies." (PMID 29866992, 2018). "Filaggrin is central to the pathogenesis of atopic dermatitis (AD)." (PMID 29691836, 2018). "In addition, the pathomechanisms of filaggrin or filaggrin-modifying natural moisturizing factors in atopic dermatitis are complex and more works are required to establish influences FLG-SNVs on epidermal barrier defects." (PMID 29281699, 2017). "Filaggrin (FLG), a key component of the cornified envelope of the stratum corneum that links keratin fibers, has a high rate (up to 47%) of mutation in many European atopic dermatitis patients leading to decreased skin barrier function." (PMID 27983701, 2016).
atopic dermatitis (continued). "There are reports of various null-mutations in the FLG gene (R501X, 2282del4 and subsequently others) that produce a decrease or absence of filaggrin in the skin and predispose to ichthyosis vulgaris and atopic dermatitis." (PMID 27462351, 2016). "Several null-mutations in the FLG gene that produce a decrease or absence of filaggrin in the skin and predispose to atopic dermatitis and ichthyosis vulgaris have been described." (PMID 27462351, 2016). "Mutations in the filaggrin gene have shown great importance in ichthyosis vulgaris and atopic dermatitis, but no clear relationship to asthma has been deduced." (PMID 27462351, 2016). "Non-functional mutations in filaggrin, a protein binding to and condensing the keratin cytoskeleton, are risk factors for asthma, atopic eczema and allergies." (PMID 26672748, 2015). "Abnormalities of the filaggrin gene are seen in some patients with atopic dermatitis." (PMID 25648414, 2015). "In addition to a genetic basis for a compromised skin barrier, elevated expression of Th2-type cytokines such as interleukin (IL)-4 and IL-13 in the skin of individuals with atopic dermatitis decreases filaggrin expression." (PMID 26573531, 2015). "c.3321delA is the most common filaggrin gene mutation in Chinese atopic dermatitis patients but is not present in European populations." (PMID 24858702, 2014). "In contrast to acquired filaggrin deficiency, reduced FLG expression can also be inherited by loss-of-function mutations in FLG, which have been demonstrated in patients with atopic dermatitis, psoriasis and ichthyosis vulgaris and potentially occur in canine atopy." (PMID 23398847, 2013). "Moreover, the EDC contains the filaggrin gene (FLG), mutations in which are well-known atopic dermatitis susceptibility factors." (PMID 22284537, 2012). "Filaggrin gene (FLG) loss-of-function mutations underlie ichthyosis vulgaris, a semi-dominant disorder of keratinization, and are the strongest and most widely replicated genetic risk factor for atopic dermatitis (AD)." (PMID 21261659, 2011). "Filaggrin (FLG) has a central role in the pathogenesis of atopic dermatitis (AD)." (PMID 20621340, 2010). "However, also in patients without filaggrin mutations, alanine, histidine and proline showed a significant negative correlation with the severity of atopic dermatitis." (PMID 41002986, 2025). "In addition, OVOL1 inhibition was involved in Filaggrin reduction, which might be involved in atopic dermatitis pathogenesis." (PMID 38907248, 2024). "α-13’-COOH increased expression of filaggrin, a key protein for epidermal structure and barrier function, in atopic dermatitis skin model m3 compared to the untreated disease control model; thus, this vitamin-E derivative may have promising strengthening effects on the skin barrier." (PMID 36615633, 2023). "Absence of filaggrin in null carriers predisposes to ichthyosis vulgaris, and/or atopic dermatitis." (PMID 36751320, 2023). "Therefore, strategies that involve blocking the cytokine-mediated FLG downregulation or enhancing FLG expression may be beneficial in treating atopic dermatitis." (PMID 36904070, 2023). "The aim of our current study was to assess the association between the susceptibility to childhood atopic eczema as well as eczema-associated asthma and genetic variants in the HRNR and FLG2 genes, two worthy investigation members of the S-100-fused type protein family, which also includes FLG." (PMID 36013110, 2022). "Nevertheless, the FLG gene is only one of 70 genes located in the EDC on chromosome 1q21; genetic and experimental studies have indicated that FLG mutations may not be solely responsible for the strong genetic association between this region and atopic eczema." (PMID 36013110, 2022).
atopic dermatitis (continued). "Based on our findings it may be inferred that dogs with atopic dermatitis manifest skin lesions along with the inflammatory response, and the skin barrier proteins (Filaggrin and Involucrin) and inflammatory cytokines (TNF-α, IL-31, IL-13) seem to be key players in the pathogenesis of AD in dogs." (PMID 34075152, 2021). "The downregulation of miR-143 in atopic dermatitis stimulates the activity of IL-13 secreted by activated Th2 cells by targeting interleukin 13 receptor subunit α1 (IL-13Rα1), resulting in reduced expression of filaggrin and components of cornified envelope proteins such as involucrin and loricrin." (PMID 32806619, 2020). "Well-established mechanisms of the action of filaggrin on the maintenance of structural and functional epidermal barrier homeostasis may contribute to the gradual expansion of the role of filaggrin in skin disorders other than atopic dermatitis." (PMID 32054030, 2020). "Conversely, although a significant filaggrin loss-of-function mutation-related skin-barrier defect is often observed in patients with atopic eczema, such a defect could not be detected in men with genital LS9." (PMID 32518626, 2020). "However, 40% of filaggrin mutation carriers do not develop atopic dermatitis, and filaggrin mutations are only found in 15%–50% of patients with atopic dermatitis." (PMID 32326002, 2020). "It is apparent that not all patients with filaggrin deficiency go on to develop atopic dermatitis." (PMID 22619686, 2012). "Filaggrin gene defects may exist in as many as 50% of atopic dermatitis patients." (PMID 22619686, 2012). "The critical role of filaggrin in epidermis homeostasis and barrier function has been evidenced by the recent disclosure that loss-of-function mutations in the filaggrin gene underlie ichthyosis vulgaris (OMIM #146700) and are strong predisposing factors for atopic dermatitis (OMIM %603165)." (PMID 18923650, 2008). "The expression of claudin, cyclin B1, cyclin D1, filaggrin, phospho-histone H2AX, kallikrein 7, Ki67, loricrin, NFAT5, and periplakin was assessed on punch biopsies obtained from eight psoriasis and six atopic eczema patients." (PMID 40559228, 2025). "In atopic dermatitis, it was found that AHR signaling increased the expression of OVOL1, which after its passage to the nucleus increased Filaggrin." (PMID 38907248, 2024). "It is interesting to note that schaftoside significantly upregulated the expression of filaggrin, thereby suggesting that schaftoside could be a useful natural bioactive component in the future treatment of some of the most common dermatological diseases, such as atopic dermatitis and psoriasis." (PMID 39684479, 2024). "Genetic variants of filaggrin (FLG) are found in 15–40% of atopic dermatitis patients, and decreased levels of filaggrin and filaggrin-like proteins (hornerin and filaggrin family member 2) are found in lesional and non-lesional skin of atopic dermatitis patients." (PMID 39202657, 2024). "Transcript levels of the skin barrier proteins CK10, FLG and IVL were significantly reduced in atopic dermatitis skin models m2 and m3 (p < 0.001)." (PMID 36615633, 2023). "For example, coal tar, used as a treatment for atopic dermatitis, has been reported to increase the expression of NQO1 and Filaggrin via AhR." (PMID 34884772, 2021). "The gene expression of FLG, FLG2, LOR, IVL, and S100A7 is differentially affected in atopic dermatitis (AD) and psoriasis." (PMID 32751111, 2020). "Skin barrier dysfunction, including reduced filaggrin (FLG) and loricrin (LOR) expression, plays a critical role in atopic dermatitis (AD) development." (PMID 33321923, 2020). "Our data clearly show that the levels of filaggrin protein, eosinophil MBP and total IgE were increased in pediatric patients with atopic dermatitis, allergic rhinitis and bronchial asthma." (PMID 30473631, 2018).
atopic dermatitis (continued). "The expression of FLG, LOR, and IVL is downregulated in the lesional skin of atopic dermatitis and is restored by appropriate treatments." (PMID 29866992, 2018). "We showed that elevated expression of AQP3 led to a reduced expression of differentiation markers, filaggrin in particular and an increased expression of CCL5 and TNFα, two of the most prominent cytokines in atopic dermatitis." (PMID 24260356, 2013). "Moreover, in our earlier study, we observed increased expression of the epidermal barrier protein filaggrin in CSU lesions, correlating with disease severity, whereas filaggrin was downregulated in the skin of those with atopic dermatitis." (PMID 41498512, 2026). "At the mRNA level, involucrin and occludin were downregulated, while the expression of filaggrin, loricrin, claudin-1, and Tjp1 was not changed in NC/Nga mice with atopic dermatitis." (PMID 37298299, 2023). "Conventionally, however, the filaggrin expression is reduced or absent in hyperproliferative diseases, such as psoriasis and atopic dermatitis." (PMID 37047109, 2023). "In a model of atopic dermatitis using a reconstructed canine epidermis, the active ingredients of ATOP 7® spot-on seemed to lead to an improvement in the morphology of the epidermis, an increase in filaggrin expression and a decrease in IL-8 secretion." (PMID 36006305, 2022). "Given that the HRNR protein has many structural and functional similarities to FLG, abnormalities in HRNR expression could be involved in the skin barrier dysfunction in atopic eczema." (PMID 36013110, 2022). "Decreases in ceramide in both lesional and non-lesional skin of patients with atopic dermatitis are uniquely observed, especially in those with filaggrin abnormalities." (PMID 32326002, 2020). "The evident expression of filaggrin and involucrin in lesional skin does not support a pathogenesis of atopic eczema." (PMID 32333380, 2020). "Since genetic abnormalities in filaggrin alone do not explain all the skin barrier dysfunctions of atopic dermatitis, further research is needed to clarify the contribution of environmental and other possible factors to this condition." (PMID 32326002, 2020). "This has confirmed the presence of wide-ranging defects in the cornification occurring in atopic dermatitis but, unfortunately, does not permit any connection to be made between them and the eventual occurrence of a filaggrin defect." (PMID 25378284, 2015). "Aside from filaggrin, loricrin and involucrin are also downregulated by IL-4 and IL-13 in lesional and non-lesional atopic dermatitis skin, contributing to a defective skin barrier that allows penetration of bacteria and allergens into the skin, leading to infections and allergen sensitization." (PMID 39202657, 2024). "In primary keratinocytes, atopic dermatitis cytokines (IL-4, IL-13 and IL-31) significantly decreased mRNA expression of the barrier structure protein filaggrin (FLG) without histamine (0.3 ± 0.06-fold, p < 0.001) and in combination with histamine (0.24 ± 0.04-fold; p < 0.001)." (PMID 36615633, 2023). "Recent GWASs have identified that other genes in the epidermal differentiation complex (EDC) such as hornerin, FLG2, involucrin and loricrin could impair skin barrier function in patients with atopic dermatitis, regardless of their FLG genotype." (PMID 36904070, 2023). "In conclusion, the present study indicates that risk variants in HRNR and FLG2 genes may contribute to atopic eczema susceptibility; for HRNR SNP, this effect seems to be independent of the well-established FLG risk alleles." (PMID 36013110, 2022). "Which filaggrin is of most relevance in canine atopic dermatitis is not known." (PMID 35878346, 2022). "An endotype for severe atopic dermatitis in children was characterized by reduced filaggrin (FLG) in non-lesional skin, suggesting that AD may begin with barrier dysfunction rather than the appearance of eczema (lesions)." (PMID 34665817, 2021).
atopic dermatitis (continued). "Thus, manipulating FLG expression may consequently alter HRNR expression, whereby it should be noted that the latter protein plays a role in atopic dermatitis." (PMID 34572044, 2021). "Recent studies have shown that in addition to filaggrin abnormalities, abnormalities in the filaggrin-like proteins, hornerin and Filaggrin family member 2 (FLG2), are also involved in either the lesional or non-lesional skin barrier symptoms of atopic dermatitis." (PMID 32326002, 2020).